EPHB2 (EPH receptor B2)
Diseases named in the same sentence as EPHB2 in open-access papers (continued):
Sharing a sentence is not in itself a finding about the gene and the disease.
bladder tumor (1 paper, 2014). "In contrast EphB2 appears to be highly expressed in normal urothelium and is lost in bladder tumor." (PMID 25148033, 2014).
bone cancer (1 paper, 2025). A primary or metastatic malignant neoplasm affecting the bone or articular cartilage. "Activation of EphrinB2/EphB2 signaling in dorsal root ganglia and dorsal horn neurons enhances dorsal horn synaptic plasticity and contributes to bone cancer pain." (PMID 41394876, 2025).
cardiac amyloidosis (1 paper, 2025). Cardiac amyloidosis is a condition whereby cardiac tissue is infiltrated by amyloid fibrils. "SERPINA1 reduces the risk of cardiac amyloidosis by inhibiting plasmin-mediated transthyretin hydrolysis and aggregation; it modulates the Eph receptor B2 signaling pathway to improve energy metabolism and glucose homeostasis, thereby influencing cardiometabolic diseases." (PMID 41287052, 2025).
cardiac hypertrophy (1 paper, 2024). "Developmental SHP2 dysfunction underlies cardiac hypertrophy in Noonan syndrome partially through the decreased NOTCH1/EPHB2 signaling." (PMID 39329089, 2024).
Cerebral ischemia (1 paper, 2019). Restriction of arterial blood supply to the brain associated with insufficient oxygenation to support the metabolic requirements of the tissue. "In light of the importance of NMDAR-mediated excitotoxicity during cerebral ischemia, we consequently aimed at analyzing the function of NMDARs in EphB2-deficient neurons in the context of excitotoxicity." (PMID 30722785, 2019). "Our MRI studies revealed a reduced cytotoxic edema in the infarct core of Ephb2-deficient mice already 6 h after cerebral ischemia, and thus point to a potential relationship between neuronal EphB2 function and the extent of glutamate excitotoxicity during ischemic stroke." (PMID 30722785, 2019). "Along this line, we showed for the first time that EphB2 is rapidly activated in the CNS of mice suffering from cerebral ischemia." (PMID 30722785, 2019). "Cerebral ischemia was induced in Ephb2−/− mice by transient middle cerebral artery occlusion followed by different times (6, 12, 24 and 48 h) of reperfusion." (PMID 30722785, 2019).
chordoma (1 paper, 2011). Chordomas are rare malignant tumors arising from embryonic remnants of the notochord in axial skeleton. "The activation of EPHB2 was recently described in one chordoma study." (PMID 22613809, 2011). "The role of EPHB2 in chordoma development and progression needs to be further evaluated." (PMID 22613809, 2011). "Using the same RTK antibody array, Shalaby and colleagues recently showed activation of HER2, MSPR, EPHB2 and MER for the U-CH1 chordoma cell line and the three tested chordoma cases." (PMID 22613809, 2011). "Importantly, we also found two other RTK: EPHB2 and MSPR, to be significantly activated in chordoma." (PMID 22613809, 2011). "Thus, the EPHB2, EGFR and macrophage-stimulating protein receptor (MSPR) were found to be significantly activated in chordoma." (PMID 22613809, 2011).
cognitive decline (1 paper, 2016). "Important future tasks will be testing whether exogenous miR‐204 in the hippocampus can induce early cognitive decline in mice and whether an antagomir of miR‐204 can restore EphB2 signaling and rescue NMDAR‐dependent LTP in aged mice." (PMID 26799631, 2016).
craniosynostosis (1 paper, 2023). Craniosynostosis is defined as the premature fusion of one or more cranial sutures leading to secondary distortion of skull shape resulting in skull deformities with a variable presentation. "Therefore, Ephb2 may work together with Ephb3 as seen during palate formation but downstream of Ephb3 during craniosynostosis." (PMID 37378024, 2023).
diabetic retinopathy (1 paper, 2021). "The vascular density in diabetic retinopathy tissues was significantly greater than that seen in retinopathy of prematurity tissues, where there was also much less expression of ephrinB2, EphB2, and EphB3 (25%, 70%, and 45% respectively)." (PMID 34201393, 2021).
gastric tumours (1 paper, 2020). "The results showed that EphB2 expression was significantly upregulated in gastric tumours compared to normal tissue (P=0.0020)." (PMID 32226496, 2020).
glaucoma (1 paper, 2020). Increased pressure in the eyeball due to obstruction of the outflow of aqueous humor. "Interestingly, we found 8 genes (FN1, THBS1, EPHB2, FGF2, DAB2, CD9, PLAUR and ITGA4) were crucial, suggesting that these genes might function as key factors in the pathogenesis of glaucoma." (PMID 31680442, 2020).
hereditary colorectal cancer (1 paper, 2008). "Rare germline EPHB2 variants may contribute to a small fraction of hereditary colorectal cancer." (PMID 18682749, 2008). "The aim of this study was to evaluate the contribution of EPHB2 to hereditary colorectal cancer." (PMID 18682749, 2008).
hypospadias (1 paper, 2014). Hypospadias is the displacement of the urethral meatus on the ventrum of the penis. "Of relevance to genitourinary tract development, EphB2 mutations result in hypospadias and cloaca in mouse models which implies a role for EphB2 in the midline fusion of the anus and lower urinary tract during development." (PMID 25148033, 2014).
IgA nephropathy (1 paper, 2026). "Transcriptomic-wide MR identified candidate genes across GN subtypes: RECQL, BRSK2, and MGP in acute GN; AFM, CFHR5, and EPHB2 in chronic GN; IL6R, MBL2, and PRSS3 in IgA nephropathy; and TIMP4, HCK, and PEAR1 in membranous nephropathy." (PMID 41990104, 2026).
intestinal inflammation (1 paper, 2021). "In this study, we evaluated the role of EphB2/ephrin-B1 axis in the enrichment of EVs in the damaged colon and the effects of EphB2-EVs on DSS-induced intestinal inflammation." (PMID 33722292, 2021).
ischemia (1 paper, 2019). A hypoperfusion of the BLOOD through an organ or tissue caused by a PATHOLOGIC CONSTRICTION or obstruction of its BLOOD VESSELS, or an absence of BLOOD CIRCULATION. "The early phosphorylation of EphB2 after the onset of ischemia, prompted us finally to have a closer look at its ligand ephrin-B2." (PMID 30722785, 2019).
ischemic stroke (1 paper, 2019). A stroke disorder caused by obstruction of blood flow to the brain, due to thrombotic (local blood clot formation) or embolic (due to a blood clot or other material traveling from another site) event. "Given the reduced neuronal cell death and extent of acute cytotoxic edema in Ephb2-deficient mice upon ischemic stroke, we hypothesized that in this context EphB2 activation contributes to neuronal excitotoxicity." (PMID 30722785, 2019). "Decreased brain tissue damage in Ephb2−/− mice was further associated with reduced Bederson neurological severity scores and improved motor dysfunction during the acute stage of ischemic stroke." (PMID 30722785, 2019). "In the light of those findings, our present study aimed to investigate the impact of EphB2 on the outcome of ischemic stroke and the responses of brain parenchymal cells." (PMID 30722785, 2019). "To the best of our knowledge, we here provide the first experimental evidence that EphB2-dependent signaling is crucial for certain pathophysiological processes that are initiated in the early acute phase after ischemic stroke." (PMID 30722785, 2019). "Overall, our experimental data strongly suggest that glutamate-induced excitotoxic neuronal damage and inflammation during early acute ischemic stroke is substantially enhanced by EphB2/ephrin-B2 forward and reverse signaling in neurons and astrocytes, respectively." (PMID 30722785, 2019). "However, Ephb2−/− mice showed markedly reduced neuronal cell death across the infarct lesion during the hyperacute phase of ischemic stroke." (PMID 30722785, 2019). "The post-ischemic BBB leakage of EB upon 12 and 24 h of reperfusion was not significantly different between Ephb2−/− and WT animals, suggesting that lack of EphB2 has no relevant direct influence on the BBB hyperpermeability during acute ischemic stroke." (PMID 30722785, 2019).
lentivirus infection (1 paper, 2023). Virus diseases caused by the Lentivirus genus. "Transwell migration assay demonstrated that EPHB2 siRNA-suppressed Schwann cell migration was rescued by FOSL1-overexpressing lentivirus infection." (PMID 37949219, 2023). "EdU proliferation assay showed that FOSL1-overexpressing lentivirus infection recovered the relative proliferation rate from about 57.19% of the control group in the EPHB2 siRNA transfected group to about 80.69%." (PMID 37949219, 2023).
lung fibrosis (1 paper, 2023). "Cleavage of EPHB2 by ADAM10 in fibroblasts induces their activation and increases skin and lung fibrosis." (PMID 36835058, 2023).
mesothelioma (1 paper, 2025). A usually malignant and aggressive neoplasm of the mesothelium which is often associated with exposure to asbestos. "Silencing EphB2 in mesothelioma cell lines resulted in a pronounced reduction in downstream effectors including matrix metalloproteinase-2 and vascular endothelial growth factor, while the expression of pro-apoptotic mediators such as caspase-8 was upregulated." (PMID 40943224, 2025).
metastatic prostate carcinoma (1 paper, 2018). A carcinoma that arises from the prostate gland and has spread to other anatomic sites. "Specimens from metastatic prostate carcinoma showed missense and nonsense mutations in the kinase domain of EphB2, and transfection of normal EphB2 in DU145 cell line led to the suppression of growth and colony formation." (PMID 29682554, 2018).
mucositis (1 paper, 2024). Mucositis is inflammation and damage of the mucous membranes lining the mouth and other parts of the gastrointestinal (GI) tract. "Thus, on the one hand, EphB2 loss might be a factor of tissue damage that accompanies the severe mucositis; on the other hand, this MOA might be beneficial as an anticancer or a chemoprevention effect of 5-FU if EphB2 down-regulation holds true at lower drug doses." (PMID 39682211, 2024).
myeloma (1 paper, 2020). "Activation of endothelial ephrinB2 reverse signaling with soluble EphB2 or EphB2 overexpressing mouse myeloma cells showed a translocation of vascular endothelial cadherin (VE-cadherin) and enhanced endothelial permeability." (PMID 32781521, 2020).
myocardial infarction (1 paper, 2020). Gross necrosis of the myocardium, as a result of interruption of the blood supply to the area, as in coronary thrombosis. "In addition, the EPH receptor genes EPHA2, EPHA8, and EPHB2 are located on chromosome 1 within region 1p34‐36, which has been identified as a locus for myocardial infarction by a genome wide search for susceptibility genes for myocardial infarction." (PMID 32337793, 2020).
neurotoxicity (1 paper, 2025). Toxicity that causes injury to the central or peripheral nervous system or damages its function. "Neurotoxicity is a pathological phenomenon seen in neuroHIV that was also observed through transfer of cell-free CM from Ephb2 activated microglia onto neurons, which our data suggest is a consequence of the assortment of pro-inflammatory secreted factors (IL-6, CXCL10, TNFα, IL-1β etc.)." (PMID 40588746, 2025).
Ovarian cyst (1 paper, 2006). The presence of one or more cysts of the ovary. "Hence EphA1, EphA2, EphB2, EphB3, EphB6, ephrin A1, ephrin A5 and ephrin B1 were selected for further analysis in an additional fourteen tumor samples, one ovarian cyst and one ovarian adenoma." (PMID 16737551, 2006).
peripheral nerve injury (1 paper, 2023). Injury to a peripheral nerve. "In addition to the positive regulation of FOSL1 on EPHB2, the dynamic changes of FOSL1 and EPHB2 following peripheral nerve injury were also comparable." (PMID 37949219, 2023).
pharyngeal cancer (1 paper, 2020). "A recent study reported that oral tongue (OSC19 and SCC61) or pharyngeal cancer (Detroit 562) cell-derived sEVs can induce Ephrin-B reverse signaling in endothelial cells and promote angiogenesis via Ephrin type B receptor 2 (EPHB2)." (PMID 33158181, 2020).
psoriasis (1 paper, 2025). An autoimmune condition characterized by red, well-delineated plaques with silvery scales that are usually on the extensor surfaces and scalp. "There is no direct evidence that EPHB2 is involved in the pathogenesis of psoriasis, but previous studies have supported that EPHB2 is involved in Th17 cell differentiation and plays a key role in the antifungal signaling pathway." (PMID 40560938, 2025).
rheumatic diseases (1 paper, 2016). "When tested on more than one hundred sera from patients with SSc, only anti-EphB2 and anti-THEX1 autoantibodies remained statistically more often present in SSc sera compared to other sera from healthy controls or other rheumatic diseases (RA, PsA and AS) in our ELISA conditions." (PMID 27617966, 2016). "Only EphB2 and THEX1 remained significantly recognized by respectively 34% and 60% of sera samples from patients with SSc compared to 14% and 28% (P = 2.10−4, P = 3.10−8) of sera samples from all controls including sera samples from healthy controls and from patients with other rheumatic diseases." (PMID 27617966, 2016).
supratentorial ependymoma (1 paper, 2025). A high grade ependymoma that is located within the supratentorial brain. "The EphB2-driven model exhibits high penetrance and recapitulates the histology and transcriptomic features of the corresponding human supratentorial ependymoma." (PMID 40943224, 2025).
synovial sarcoma (1 paper, 2022). "Consequently, an EPHB2-mediated cytoskeletal remodeling is observed, which is characterized by the elongation and narrowing of synovial sarcoma cells, producing neurite-like extensions." (PMID 35563562, 2022).
thrombosis (1 paper, 2024). "Among them, mutations in ABCA13, FLT1, NRP1, SWAP70 and SLC15A4 are strongly associated with immunity or proliferation, whereas mutations in VWF, SELP and EPHB2 are associated mainly with thrombosis." (PMID 39671267, 2024). "In addition, we found that a greater proportion of patients with thrombosis than patients without thrombosis carried EpHB2 mutations (p = 0.015), SWAP70 mutations (p = 0.039), ABCA13 mutations (p = 0.01) and SLC15A4 mutations (p = 0.004)." (PMID 39671267, 2024).
ulcer (1 paper, 2013). "In a mouse ulcer model, EphB2 expression was upregulated in the regenerating epithelium and expanded into the isthmus while ephrin-B1 expression was in pit cells and proliferating cells of the isthmus, where stem cells are located and EphB2-ephrin B1 bidirectional signaling is activated." (PMID 23874863, 2013).
viral infection (1 paper, 2025). "Although IRF7 may not be mediating the IFNβ induced expression of EphB2, the ablation of IRF7 alone does induce transcription of IRF3, the long-non-coding RNA HEAL and NF-kB, three factors implicated in viral infection and inflammation." (PMID 40588746, 2025).
tumor (134 papers, 2003 to 2026). "Genetic and transcriptome analyses implicated that EphB2 is a therapeutic target for specific tumor types." (PMID 40943224, 2025). "Loss of EphB2 has already been shown to correlate with reduced tumor growth, CRC progression, and adverse patient outcomes, and promotion of liver metastasis." (PMID 38651144, 2024). "EphB2 has a complex role, in which its overexpression is associated with tumor progression, and downregulation correlates with worse outcomes." (PMID 39839790, 2024). "EphB2 is situated on the region of chromosome 1, called p35–36, and has been suggested as a potential tumour suppressor gene because of its association with recurrent allelic inactivation in colorectal cancers." (PMID 36830852, 2023). "Glutamine metabolism is significantly activated in tumor cells in hypoxic microenvironment, whereas EPHB2 is significantly associated with glutamine metabolism." (PMID 37091977, 2023). "Subsequent studies showed that that ephrin-B1 controls the distribution and spread of EphB2- and EphB3-expressing tumour cells in the colon, which is overcome during tumour progression by the loss of EphB expression." (PMID 36830852, 2023). "Another study has demonstrated that EPHB2 expression regulates angiogenesis both in vitro and in vivo and that EPHB2 overexpression is associated with poor prognosis and tumor angiogenesis in HNSCC patients." (PMID 36203528, 2022). "To note, in a previous study on kinome expression profiling of NB tumours, it was observed a marked overexpression of EPHB2 gene in a subset of ultra‐high‐risk NB, with highly aggressive clinical behaviour that not adequately respond to standard treatments." (PMID 32336043, 2020). "miR-31 has emerged as a potential driver for the colon oncogenesis via targeting EphB2 and EphA2 signaling pathways associated with the regulation of stemness, differentiation, tumor heterogeneity, and poor therapeutic outcomes in CRC patients." (PMID 31530793, 2019). "This suggests that EPHB2 may interact with these mutations to influence tumor behavior and patient outcomes." (PMID 41322437, 2025). "Indeed, in this significant cohort, loss of EphB2 expression correlated with an unfavorable tumor phenotype, with advanced tumor stage, high grade, presence of vascular invasion, infiltrative tumor growth, nodal metastasis, and poor survival." (PMID 38651144, 2024). "However, in adult studies, tumor samples were extensively screened, and several mutations were associated with cancer development (e.g., p35-36 region of chromosome 1 for EPHB2)." (PMID 38612645, 2024). "Moreover, in the presence of high EphB2 expression, elevated ephrin-B2 levels can cause a more aggressive tumor phenotype." (PMID 35223830, 2022). "The EphB2 level was analysed according to the degree of tumour differentiation (poorly differentiated, p/d; well-differentiated, w/d; and moderately differentiated, m/d) to evaluate the association between tumour malignancy and EphB2." (PMID 35949596, 2022). "Thus, accumulating evidence suggests that loss of EphB2 expression, in concert with a gain of EphB4 expression, is a common pathway towards switch from normal to tumor development and progression." (PMID 25148033, 2014). "Moreover, EPHB2 is associated with poor patient prognosis, and reducing its expression may inhibit tumor progression." (PMID 41322437, 2025). "Besides the EphB in normal gastric mucosa, the combined expression of EphB2, B3, and B4 with ephrinB1 was associated with gastric dysplasia, showing that EphB-ephrin-B dysfunctions may contribute to tumor development and progression." (PMID 39839790, 2024). "HIF and EPHB2 are closely associated in the gene regulatory network, hypoxia induces upregulation of EPHB2 expression and affects the invasive metastatic potential of tumors, whereas EPHB2 carried by tumor cell vesicles induces angiogenesis around tumors by activating the ephrin signaling pathway." (PMID 37091977, 2023).